VKORC1L1 (vitamin K epoxide reductase complex subunit 1L1)
Description:
Involved in vitamin K metabolism. Can reduce inactive vitamin K 2,3-epoxide to active vitamin K, and may contribute to vitamin K-mediated protection against oxidative stress. Plays a role in vitamin K-dependent gamma-carboxylation of Glu residues in target proteins.
Tractability: Small molecule: it belongs to a druggable protein family. Antibody: UniProt predicts a signal peptide or a membrane-spanning region. PROTAC: ubiquitination databases record sites on it; its protein half-life has been measured.
Target class: Enzyme; Oxidoreductase
Gene: Protein-coding gene on chromosome 7 (65,873,074 to 65,959,563, forward strand). Ensembl gene ENSG00000196715.
Subcellular location: Endoplasmic reticulum membrane
Subcellular location (Human Protein Atlas): Endoplasmic reticulum
Pathways (Reactome):
Metabolism: Metabolism of vitamin K
Gene Ontology:
Molecular function: protein binding; vitamin-K-epoxide reductase (warfarin-sensitive) activity; oxidoreductase activity, acting on CH or CH2 groups, disulfide as acceptor
Biological process: cellular response to oxidative stress; peptidyl-glutamic acid carboxylation; vitamin K metabolic process
Cellular component: endoplasmic reticulum; endoplasmic reticulum membrane
Genetic constraint (gnomAD): Loss-of-function variants: 2 observed, 11.14 expected, observed/expected ratio (o/e) 0.18, 90% interval 0.072 to 0.56. The upper end of that interval is the gene's LOEUF score, 0.56, which puts it in group 2 of 6, group 1 being the genes least tolerant of losing a copy. Missense variants: 113 observed, 154.96 expected, observed/expected ratio (o/e) 0.73, 90% interval 0.62 to 0.85. Synonymous variants: 90 observed, 72.58 expected, observed/expected ratio (o/e) 1.24, 90% interval 1.04 to 1.48.
Homologues: Orthologues: chimpanzee VKORC1L1 (100% identical), macaque VKORC1L1 (98% identical), pig VKORC1L1 (98% identical), dog VKORC1L1 (98% identical), mouse Vkorc1l1 (97% identical), tropical clawed frog vkorc1l1 (79% identical), zebrafish vkorc1l1 (71% identical), guinea pig VKORC1L1 (61% identical). Paralogues in human: VKORC1 (41% identical).
Diseases named in the same sentence as VKORC1L1 in open-access papers:
VKORC1L1 is named in the same sentence as 13 diseases in open-access papers, as found by Europe PMC text mining. Sharing a sentence is not in itself a finding about the gene and the disease. The quoted sentences say what the papers report.
breast carcinoma (3 papers, 2019 to 2025). "All three genes involved in the vitamin K cycle (GGCX, VKORC1, and VKORC1L1) are expressed in normal mouse mammary gland yet there is no published data regarding their expression in human breast or breast cancer." (PMID 31040920, 2019). "Interestingly, while each of the lung, melanoma and breast cancer persister cell types we analyzed here are deficient in one or more anti-ferroptotic factors including NRF2, GSH or in anti-ferroptotic enzymes GPX4, DHODH or VKORC1L1, all were deficient in FSP1." (PMID 40909720, 2025). "Using TissueScan arrays representing 4 normal tissues and 44 breast cancers, we confirmed up-regulation of GGCX and VKORC1L1 in a subset of tumors beginning as early as Stage IIA." (PMID 31040920, 2019). "To mechanistically address the role of vitamin K and γ-carboxylation in breast cancer, we screened a panel of breast cancer cell models for GGCX, VKORC1, and VKORC1L1 expression." (PMID 31040920, 2019). "To gain insight into the potential impact of the vitamin K pathway in breast cancer, we annotated expression of GGCX, VKORC1, and VKORC1L1, profiled GLA protein modifications, and directly compared the effects of K1 and K2 in multiple breast cancer model systems." (PMID 31040920, 2019). "To explore the relevance of γ-carboxylation in breast cancer, we first analyzed datasets from The Cancer Genome Atlas (TCGA) and found that approximately 25% of 1098 invasive breast cancers exhibit amplification or up-regulation of GGCX, VKORC1, and/or VKORC1L1." (PMID 31040920, 2019).
melanoma (2 papers, 2024 to 2025). A malignant, usually aggressive tumor composed of atypical, neoplastic melanocytes. "Vitamin K epoxide reductase complex subunit 1 like 1 (VKORC1L1) generates a reduced form of vitamin K that counteracts phospholipid peroxides and protects human pancreatic and melanoma cells from ferroptosis response independent of the GSH-GPX4 pathway." (PMID 38844964, 2024).
triple-negative breast carcinoma (2 papers, 2019 to 2023). An invasive breast carcinoma which is negative for expression of estrogen receptor (ER), progesterone receptor (PR), and human epidermal growth factor receptor 2 (HER2). "qPCR results indicated highest expression of GGCX, VKORC1, and VKORC1L1 in triple negative breast cancer (TNBC) cell lines, Hs578T, MDA-MB-231 and SUM159PT, and in advanced stage disease." (PMID 31040920, 2019).
breast tumors (1 paper, 2019). "In addition, TCGA data indicated that the subset of patients whose breast tumors exhibit genomic amplification or up-regulation of GGCX, VKORC1, and VKORC1L1 had significantly reduced overall survival." (PMID 31040920, 2019).
coronary artery disease (1 paper, 2021). "Thus far, there is no data regarding the significance of VKORC1L1 in cardiovascular diseases, although a recent mRNA expression analysis described VKORC1L1 as a putative oxidative-stress-related gene in coronary artery disease." (PMID 34778390, 2021).
Insulin resistance (1 paper, 2019). Increased resistance towards insulin, that is, diminished effectiveness of insulin in reducing blood glucose levels. "Vitamin K epoxide reductase complex, subunit 1-like 1 (VKORC1L1), BTD, GPC1, MOCOS, GPC5, AKR1C4, and NMNAT2 are novel biomarkers for the development of insulin resistance." (PMID 30678306, 2019).
invasive breast carcinoma (1 paper, 2019). A carcinoma that infiltrates the breast parenchyma. "Collectively, the available genomic and proteomic data suggest that the vitamin K-dependent pathway genes, GGCX, VKORC1, and VKORC1L1, are present in normal mammary gland but up-regulated in a subset of invasive breast cancers that are characterized by poor overall survival." (PMID 31040920, 2019).
keratoconus (1 paper, 2021). A degenerative, structural disorder of the eye, characterized by a cone-shaped protrusion of the cornea. "More studies are needed to elucidate the exact functions of VKORC1L1 in association with CCT, and explore whether/how it is involved in the pathogenesis of POAG and keratoconus." (PMID 34233613, 2021).
cancer (2 papers, 2023 to 2025). A tumor composed of atypical neoplastic, often pleomorphic cells that invade other tissues. "Moreover, the FDA-approved anticoagulant drug warfarin, a small-molecule inhibitor of VKORC1L1, suppresses tumor growth by inducing ferroptotic cell death in vivo, indicating that warfarin may be a potential anticancer drug, especially for cancer patients with high VKORC1L1 expression." (PMID 37739961, 2023).
tumor (2 papers, 2023 to 2025). "ScRNA‐seq data show that vitamin K cycle genes(NQO1, UBIAD1, GGCX, VKORC1, VKORC1L1) are specifically expressed in tumor cells." (PMID 41028931, 2025).
VKORC1L1 also shares sentences with these, for which no sentence is quoted: Alzheimer disease (1 paper); cardiovascular diseases (1); eosinophilia (1).